PRAME (PRAME nuclear receptor transcriptional regulator)
Diseases named in the same sentence as PRAME in open-access papers (continued):
Sharing a sentence is not in itself a finding about the gene and the disease.
acute leukemia (7 papers, 2012 to 2024). A clonal (malignant) hematopoietic disorder with an acute onset, affecting the bone marrow and the peripheral blood. "We demonstrated that fluorescent anti-PRAME antibodies allow for immunotyping bone marrow cells of patients with acute leukemia for the presence of the PRAME protein, which significantly affects the course of the disease and further prognosis." (PMID 36982208, 2023). "The candidate targets of Wilms tumor 1 (WT1), survivin (BIRC5), and PRAME were selected given the high prevalence in relapsed and refractory acute leukemias (77-81% for WT1, 63-100% for BIRC5, and 42-87% for PRAME)." (PMID 36248870, 2022). "Among the different classification groups of acute leukemia in the present study, PRAME gene expression was highly expressed in ALL compared to other forms." (PMID 35788450, 2022). "Preferentially expressed antigen of melanoma (PRAME) gene is regularly overexpressed in acute leukemia (AL) and other malignant diseases which are recognized by human leucocyte antigen (HLA-24) located in the human chromosome of 22q11 coded by 509 amino acids." (PMID 35788450, 2022). "Differential expression between acute leukemia patients and healthy volunteers suggests that the immunogenic antigens (PRAME and WT1) are potential candidates for immunotherapy in childhood acute leukemia." (PMID 27275197, 2015). "The level of expressed PRAME mRNA in bone marrow mononuclear cells from 34 patients with acute leukemia (AL) and in 12 bone marrow samples from healthy volunteers was measured via RT-PCR." (PMID 23691459, 2012). "However, large-scale and prospective cohort studies will ultimately be needed to validate the good prognostic outcome of PRAME overexpression in acute leukemia." (PMID 33381588, 2020). "The PRAME gene is highly expressed in acute leukemia and could be a useful marker to monitor minimal residual disease." (PMID 23691459, 2012). "We hypothesized that a blood-based multiplex ddPCR assay of WT1, BIRC5 (survivin), and PRAME as a ratio against homeostatic ABL1 would detect MRD in the majority of relapsed refractory acute leukemias after HCT, at levels exceeding those of healthy individuals." (PMID 36248870, 2022). "In patients with active acute leukemia after HCT (MRD+ or relapse; n=19), the blood levels of WT1/ABL1, PRAME/ABL1, and BIRC5/ABL1 exceeded healthy donors (p<0.0001, p=0.0286, and p=0.0064 respectively)." (PMID 36248870, 2022). "However more studies on larger number of patients are needed for better understanding the roles of WT1 and PRAME genes in the process of leukemogenesis, their significance as a prognostic factor, minimal residual disease marker and being a possible target for immunotherapy in acute leukemia." (PMID 27275197, 2015). "PRAME gene expression in acute leukemia has not been studied in the Indian population in correlation with conventional cytogenetics." (PMID 35788450, 2022). "To date, WT1, BIRC5, and PRAME have not been promoted as biomarkers of relapse, likely in part due to the scant data for BIRC5 and PRAME and the lack of sensitivity for detection of relapse in prior studies of WT1 in acute leukemia." (PMID 36248870, 2022). "It is concluded that the expression of PRAME and WT1 genes are indicators of favorable prognosis and can be useful tools for monitoring minimal residual disease (MRD) in acute leukemia especially in patients without known genetic markers." (PMID 27275197, 2015).
chronic myeloid leukemia (7 papers, 2012 to 2025). "In chronic myelogenous leukemia the over expression of PRAME is also discussed as factor for drug resistance and in diffuse large B cell lymphomas high expression of PRAME is associated with resistance against cytostatic drugs." (PMID 23409080, 2013).
medulloblastoma (7 papers, 2020 to 2026). A malignant, invasive embryonal neoplasm arising from the cerebellum. "Regarding CNS tumors, the significance of PRAME expression has been investigated in medulloblastoma as a biomarker for immunotherapy." (PMID 37796789, 2023).
mucosal melanoma (7 papers, 2022 to 2025). A melanoma that arises from a mucosal site. "In addition to be a promising target for immunotherapy, PRAME was approved as a diagnostic marker for subgroups of mucosal melanoma, including urological, gynecological, and head and neck mucosal melanomas, due to its reliability." (PMID 41369373, 2025). "The differential expression of PRAME in different subtypes of mucosal melanoma therefore makes it useful to distinguish malignant melanomas from their benign counterparts." (PMID 41369373, 2025). "A retrospective study conducted on different types of mucosal melanoma (sinonasal, gastrointestinal, genitourinary, and oropharyngeal) shows the prognostic implication of PRAME expression." (PMID 35328098, 2022). "While benign mucosal melanocytic lesions and lymph node nevi show no PRAME expression, mucosal melanoma and lymph node metastases show increased PRAME expression." (PMID 38338862, 2024).
non-small cell lung carcinoma (7 papers, 2022 to 2025). A group of at least three distinct histological types of lung cancer, including non-small cell squamous cell carcinoma, adenocarcinoma, and large cell carcinoma. "One study found that high expression of PRAME inhibited tumor metastasis in non-small cell lung cancer, and some bioinformatics analyses suggested that PRAME overexpression was associated with a better prognosis." (PMID 36980687, 2023).
dysplastic nevi (6 papers, 2021 to 2025). "Immunoreactivity for PRAME was seen, albeit usually only in a minor subpopulation of lesional melanocytes, in 13.6% of cutaneous nevi, including dysplastic nevi, common acquired nevi, traumatized and recurrent nevi, and Spitz nevi (one case in a 6 years-old child)." (PMID 35328098, 2022). "In their study of 60 dysplastic nevi, no cases showed a PRAME expression of +4; instead, a score of +1 was found in 10 cases and a score of +2 in one case." (PMID 41153267, 2025). "In our cohort, one SSM was entirely PRAME-negative, whereas a subset of dysplastic nevi demonstrated diffuse positivity (+4)." (PMID 41153267, 2025).
leiomyosarcoma (6 papers, 2017 to 2025). An uncommon, aggressive malignant smooth muscle neoplasm, usually occurring in post-menopausal women. "PRAME, for example, is overexpressed in leiomyosarcoma and synovial sarcoma and BAGE and GAGE are overexpressed in rhabdomyosarcoma, liposarcoma, chondrosarcoma, and leiomyosarcoma." (PMID 30577459, 2018).
Spitz nevi (6 papers, 2022 to 2025). "Consequently, PRAME immunoreactivity is significantly lower in Spitz nevi and atypical Spitz tumors compared to their malignant counterparts." (PMID 40870546, 2025). "In other cases, such as Spitz tumours, the usefulness of PRAME as a diagnostic marker is unclear because PRAME is not consistently expressed in all Spitz nevi and atypical Spitz tumours and its absence does not necessarily indicate benignity." (PMID 38338862, 2024). "However, it is important to note that some of these lesions (one Spitz nevus, one atypical Spitz tumour, and one spitzoid melanoma) occasionally showed diffuse PRAME expression." (PMID 38338862, 2024). "Interestingly, PRAME immunoreactivity has also been observed in Spitz nevi, as well as in solar lentigines and benign uninjured skin." (PMID 38338862, 2024). "Indeed, an intriguing aspect of PRAME expression is its variability within Spitz nevi." (PMID 38338862, 2024). "The conclusion of this study aligns with earlier observations, which reported that most Spitz nevi showed no PRAME expression, only one out of eleven cases displayed diffuse positivity, and two had focal reactivity." (PMID 40868240, 2025). "Namely, it was found that most Spitz nevi and atypical Spitz tumors completely lacked PRAME expression." (PMID 40868240, 2025). "A recent study revealed that strong, diffuse PRAME positivity was present in 20% of Spitz nevi, absent in all atypical Spitz tumors, and prominent in 82% of spitzoid melanomas." (PMID 40868240, 2025). "In their cohort of cases, the results showed that most Spitz nevi and atypical Spitz tumours completely lacked PRAME expression." (PMID 38338862, 2024). "Indeed, although most benign and intermediate Spitz lesions lacked widespread PRAME expression, widespread PRAME positivity was observed in a Spitz nevus and atypical Spitz tumor." (PMID 35328098, 2022).
diffuse large B-cell lymphoma (5 papers, 2013 to 2023). "Integrative genomic analysis in diffuse large B cell lymphoma (DLBCL) uncovered recurrent and highly focal deletions of 22q11.22, including the PRAME gene, which were associated with poor outcome." (PMID 35380993, 2022). "Indeed, it remains an open question whether heterozygous or homozygous PRAME deletions can occur during the process of B cell lymphomagenesis, and potentially at the time point of the germinal center (GC) reaction in GC-derived diffuse large B cell lymphomas (DLBCLs)." (PMID 35838054, 2022).
metastatic disease (5 papers, 2019 to 2025). "Given that certain class 1A tumors still progress to metastatic disease and that PRAME+ appears to be associated with increased metastatic disease rates, a positive PRAME expression status in a GEP class 1 tumor may explain the rare cases in this group that do metastasize." (PMID 34195690, 2021). "Our multivariate regression analysis suggests that the prognostic value of PRAME expression is robust, even in relation to established clinical parameters such as surgical margins or metastatic disease." (PMID 33287125, 2020). "Finally, high PRAME expression was confirmed as a prognostic factor for overall survival in a Cox proportional hazards model that included clinical parameters like metastatic disease and surgical margins." (PMID 33287125, 2020). "This analysis revealed significantly higher expression of PRAME and RSPO2 in metastatic tumors, further supporting their potential role in disease progression." (PMID 40076569, 2025). "In multivariate analysis, high PRAME and low SSX2 expression levels as well as metastatic disease, non-radical resections, and not receiving chemotherapy are shown to be independent predictors of shorter overall survival." (PMID 33287125, 2020).
myxoid liposarcoma (5 papers, 2020 to 2025). A liposarcoma characterized by the presence of round non-lipogenic primitive mesenchymal cells and small signet ring lipoblasts within a myxoid stoma with a branching vascular pattern. "A recent sarcoma-focused immunohistochemical study confirmed 100% PRAME expression in 11 SS cases – most at the highest level of interpretable staining intensity, matched only by myxoid liposarcoma, embryonal rhabdomyosarcoma and intimal sarcoma." (PMID 40849585, 2025). "PRAME, a repressor of retinoic acid receptor-mediated differentiation and apoptosis, is expressed in 70% of SS cases (152/216), although it has also been detected at a high frequency in some other malignancies, including myxoid liposarcomas, some carcinomas, and melanomas." (PMID 40849585, 2025).
nevus (5 papers, 2021 to 2025). Nevus (or naevus, plural nevi or naevi, from nævus, Latin for "birthmark") is the medical term for sharply circumscribed[1] and chronic lesions of the skin or mucosa. "In the dysplastic nevus group, 1 case showed a score of +4, 2 cases had a score of +1, and 24 cases were negative (score 0) for PRAME expression." (PMID 41153267, 2025). "Therefore, a potential nevus diagnosis should be critically questioned in atypical non-spitzoid proliferations with diffuse PRAME expression, and a complete excision of the lesion considered." (PMID 34359765, 2021).
acral melanomas (4 papers, 2022 to 2025). "PRAME expression is highly sensitive and specific in the context of acral melanomas and is a more predictive diagnostic tool than p16 immunohistochemistry." (PMID 38338862, 2024). "In the context of acral lesions, PRAME has been shown to be a supportive marker, particularly in acral melanomas with histopathological uncertainty, offering higher sensitivity and specificity than p16." (PMID 38338862, 2024). "According to the literature, especially in acral melanomas characterised by doubtful or misleading histopathological features, PRAME assumes an important role as an immunohistochemical marker that, although not capable of confirming the diagnosis, is able to support the histological diagnosis." (PMID 38338862, 2024). "In a separate cohort, all examined cases of acral melanoma tested positive for PRAME, while none of the benign, dysplastic, or Spitz-type acral nevi showed PRAME expression." (PMID 40868240, 2025). "Furthermore, in some subungual melanomas (SUM) and non-subungual acral melanomas (AM), PRAME expression was negative, whereas in some benign nevi, it was positive." (PMID 38338862, 2024). "An immunohistochemical study investigating 22 NAMs, 20 non-NAM acral melanomas, and 14 benign acral nevi reported that 73% of NAMs, 95% of non-NAM acral melanomas were positive for PRAME at least in part, whereas only one (7%) acral nevus exhibited PRAME expression." (PMID 36983205, 2023).
bladder cancer (4 papers, 2020 to 2024). "CT10 expression has been previously reported in bladder cancer however, to the best of our knowledge, PRAME expression has not been previously studied in bladder cancer." (PMID 31485721, 2020).
cervical cancer (4 papers, 2020 to 2025). A primary or metastatic malignant neoplasm involving the cervix. "Nonetheless, the role of PRAME in cervical cancer occurrence and progression, as well as the underlying mechanism, is obscure." (PMID 36980687, 2023). "Taken together, PRAME is associated with cervical cancer occurrence and progression mediated by Wnt/β-catenin signaling, suggesting that PRAME might be a factor in manipulating cervical carcinogenesis and a potential therapeutic target." (PMID 36980687, 2023). "A recent study on cervical cancer indicates PRAME’s involvement in proliferation, invasion, migration, reduction of apoptotic cells, and facilitating G0/G1 cell-cycle by the Wnt/β-Catenin pathway." (PMID 40961095, 2025). "This study was designed to provide more evidence on the function of PRAME in the tumorigenesis of cervical cancer." (PMID 36980687, 2023). "In this study, the carcinogenesis potential of PRAME expression in cervical cancer cells was firstly investigated in vitro and in vivo." (PMID 36980687, 2023). "Our study not only confirmed the enhancement of malignant biological behaviors of PRAME expression in cervical cancer cells but also involved the related activation pathways of PRAME carcinogenesis." (PMID 36980687, 2023). "These samples were used to further analyze the relationship between PRAME expression and clinicopathologic features in cervical cancer patients." (PMID 36980687, 2023). "Taken together, PRAME was found to have a tumor-promoting role in cervical cancer through the Wnt/β-catenin pathway." (PMID 36980687, 2023). "The results of IHC, qRT-PCR, and Western blotting showed that PRAME was highly expressed in cervical cancer tissues and cells." (PMID 36980687, 2023). "In order to verify the role of PRAME in cervical cancer, the expression of PRAME protein was explored in normal tissues and cervical cancer tissues via IHC." (PMID 36980687, 2023). "Our previous research also indicated that PRAME was highly expressed in cervical cancer compared with normal tissues." (PMID 36980687, 2023). "In this research, PRAME was found to be highly expressed in cervical cancer tissues and cells compared with control groups." (PMID 36980687, 2023). "Moreover, cervical cancer cells were arrested more in the G0/G1 phase when PRAME was silenced, interfering with the progression of the cell cycle." (PMID 36980687, 2023). "In our previous study, PRAME was differentially expressed in cervical cancer and normal tissues." (PMID 36980687, 2023). "In conclusion, PRAME was highly expressed in cervical cancer tissues and cells." (PMID 36980687, 2023). "One article illustrated that overexpression of PRAME in HeLa cells induced caspase-independent cell death, suggesting that PRAME might function as a tumor suppressor in cervical cancer progression." (PMID 33997099, 2021). "Later, HeLa cells disintegrated into apoptotic bodies, suggesting that PRAME might act as a tumour suppressor gene in cervical cancer progression." (PMID 32022332, 2020). "E-cadherin protein was upregulated, and N-cadherin was downregulated in SiHa shPRAME cells, while E-cadherin was downregulated and N-cadherin was upregulated in PRAME-overexpressed C33A cells, suggesting that PRAME might affect cervical cancer metastasis by promoting EMT." (PMID 36980687, 2023). "Moreover, the models of transgenic mice could better explore the in vivo function of PRAME in cervical cancer." (PMID 36980687, 2023). "In this study, the authors discovered the multiple genes in HPV-negative cervical cancer, including PRAME, HMGA2, ETV4, MEX3A, TM7SF2, SLC19A1, and TTYH3, which could contribute to HPV-negative cervical cancer development." (PMID 33997099, 2021). "In contrast, the PRAME mRNA and protein were obviously overexpressed in the HPV-negative C33A cell line and HPV-negative cervical cancer tissues, implying that PRAME may represent a potential biomarker only for HPV-negative cervical cancers." (PMID 33997099, 2021).
cervical cancer (continued). "However, it has not been reported that PRAME regulated tumorigenesis through the Wnt/β-catenin pathway in cervical cancer." (PMID 36980687, 2023). "However, the roles and detailed mechanisms of PRAME have not been explored in cervical cancer." (PMID 36980687, 2023).
chondrosarcoma (4 papers, 2012 to 2025). A malignant cartilaginous matrix-producing mesenchymal neoplasm arising from the bone and soft tissue. "PRAME expression was highest in undifferentiated pleomorphic sarcoma (47.62%) and low in chondrosarcoma (7.69%)." (PMID 40152485, 2025). "In order to characterize the expression pattern of NY-ESO-1, LAGE-1s and PRAME in chondrosarcoma tumors, we used qRT-PCR to test the tumors of eleven chondrosarcoma patients." (PMID 22384167, 2012). "We evaluated if the immunogenic CTA's, NY-ESO-1, LAGE-1s and/or PRAME represent feasible targets in chondrosarcoma for antigen-specific T cell therapy." (PMID 22384167, 2012). "This study is the first to report the targeting of NY-ESO-1/LAGE-1s and/or PRAME in chondrosarcoma." (PMID 22384167, 2012). "We used 11 flash frozen tumors from the University of Washington tumor bank to test for the expression of NY-ESO-1, PRAME, LAGE-1s and LAGE-1L in chondrosarcoma tumors." (PMID 22384167, 2012).
hepatocellular carcinoma (4 papers, 2020 to 2025). A malignant tumor that arises from hepatocytes. "In recent studies, it has become apparent that PRAME is up-regulated following Gas6 stimulation, which is mediated through Axl/ERK1/2 signaling pathway in hepatocellular cancers." (PMID 40961095, 2025). "In preliminary experiments, viable outgrowing clones could not be generated from CRISPR-mediated full knockout of PRAME in MEL624 cells (data not shown), consistent with literature that PRAME inhibition causes cell cycle arrest and apoptosis in leukemic and hepatocellular carcinoma cells." (PMID 39659431, 2024).